CPNE8 (copine 8)
Description:
Probable calcium-dependent phospholipid-binding protein that may play a role in calcium-mediated intracellular processes.
Tractability: Antibody: its Gene Ontology location is reachable by antibodies, with medium confidence. PROTAC: ubiquitination databases record sites on it; its protein half-life has been measured.
Gene: Protein-coding gene on chromosome 12 (38,646,822 to 38,907,430, reverse strand). Ensembl gene ENSG00000139117.
Pathways (Reactome):
Signal Transduction: CDC42 GTPase cycle; RHOD GTPase cycle; RHOJ GTPase cycle; RHOQ GTPase cycle
Gene Ontology:
Molecular function: protein binding; calcium-dependent phospholipid binding
Biological process: cellular response to calcium ion; positive regulation of dendrite extension
Cellular component: extracellular exosome
Genetic constraint (gnomAD): Loss-of-function variants: 12 observed, 20.16 expected, observed/expected ratio (o/e) 0.6, 90% interval 0.38 to 0.96. The upper end of that interval is the gene's LOEUF score, 0.96, which puts it in group 4 of 6, group 1 being the genes least tolerant of losing a copy. Missense variants: 253 observed, 275.58 expected, observed/expected ratio (o/e) 0.92, 90% interval 0.83 to 1.02. Synonymous variants: 112 observed, 96.52 expected, observed/expected ratio (o/e) 1.16, 90% interval 1 to 1.36.
Homologues: Orthologues: chimpanzee CPNE8 (99% identical), pig CPNE8 (99% identical), rat Cpne8 (99% identical), mouse Cpne8 (99% identical), dog CPNE8 (91% identical), macaque CPNE8 (91% identical), tropical clawed frog cpne8 (90% identical), guinea pig CPNE8 (88% identical), rabbit CPNE8 (86% identical), zebrafish CPNE8 (70% identical), Caenorhabditis elegans nra-1 (46% identical), Caenorhabditis elegans gem-4 (45% identical). Paralogues in human: CPNE5 (80% identical), CPNE9 (75% identical), CPNE3 (50% identical), CPNE4 (50% identical), CPNE2 (50% identical), CPNE7 (49% identical), CPNE1 (48% identical), CPNE6 (48% identical).
Diseases named in the same sentence as CPNE8 in open-access papers:
CPNE8 is named in the same sentence as 16 diseases in open-access papers, as found by Europe PMC text mining. Sharing a sentence is not in itself a finding about the gene and the disease. The quoted sentences say what the papers report.
gastric cancer (8 papers, 2021 to 2025). A primary or metastatic malignant neoplasm involving the stomach. "It is worth noting that dysregulation of CPNE8, a member of the Copine family, has been associated with various diseases such as prion disease and gastric cancer in previous studies." (PMID 38034497, 2023). "CPNE8 has been implicated in the promotion of gastric cancer metastasis by modulating the focal adhesion pathway and the tumor microenvironment." (PMID 38052924, 2023). "Additionally, CPNE8 is strongly associated with tumor-associated fibroblast and immune cell infiltration, with high expression predicting poor outcomes for immune checkpoint therapy in gastric cancer." (PMID 39850884, 2024). "Little is known about the oncogenic role or biological function of copine VIII (CPNE8) in gastric cancer (GC)." (PMID 35982908, 2022). "Results of the ROC curve showed that ADAM12 and EDNRA, and CPNE8 had high value in the diagnosis of gastric cancer." (PMID 34663825, 2021). "In other study, prognosis was related to high expression of CPNE8 in gastric cancer." (PMID 39867879, 2024).
breast carcinoma (4 papers, 2011 to 2020). "Studies have also implicated CPNE8, MAGED1, and RNF144A in ovarian and breast cancers." (PMID 32849822, 2020). "Moreover, in basal-like breast cancer cells, CPNE8 is upregulated by the transcription factor ΔNp63α that stimulates cell migration and is also a target of the tumor suppressive miRNA miR-375." (PMID 31487856, 2019). "The function of CPNE8 is unknown, although other copine family members have been implicated in HER2 signaling and invasion in breast cancer." (PMID 21364760, 2011). "To prioritize non-mesenchymal genes for further investigation, we determined how the expression of FAT2, SNCA, CPNE8, NEK1 and CA12 correlated with ΔNp63α mRNA levels in breast cancer patient tumors analyzed by TCGA." (PMID 27081041, 2016).
acute myeloid leukemia (2 papers, 2021 to 2022). Acute myeloid leukemia (AML) is a group of neoplasms arising from precursor cells committed to the myeloid cell-line differentiation. "Ramsey found that in patients with acute myeloid leukemia (AML), the CPNE 8 gene can fuse with the AMLI gene to form an AML-CPNE8 chimera, thereby inhibiting AML gene transcription." (PMID 34367247, 2021). "CPNE8 could fuse with AMLI genes to form AML-CPNE8 chimeras in acute myeloid leukemia (AML) patients, thus negatively regulating the proliferation of AML cancer cells." (PMID 35982908, 2022).
prion disease (2 papers, 2013 to 2023). A transmissible disease that is caused by a protein that is able to induce abnormal folding of normal cellular proteins, leading to characteristic spongiform brain changes, which are associated with neuronal loss without an inflammatory response. "The role of Cpne8 in prion disease has not been established but it may be implicated in PrP processing and targeting as Cpne8 is a member of the copine family that are Ca2+ dependent phospholipid binding proteins thought to be involved in membrane trafficking." (PMID 23518043, 2013).
cervical cancer (1 paper, 2021). A primary or metastatic malignant neoplasm involving the cervix. "In early cervical cancer (CC), CPNE8 expression was significantly increased in CC cells with knockdown of long non-coding RNA RP11-396F22.1, suggesting that RP11-396F22.1 might enhance tumor aggressiveness by negatively regulating CPNE855." (PMID 34663825, 2021).
metastatic tumors (1 paper, 2022). "Our research revealed that CPNE8 is highly expressed in GC, with significantly higher expression in metastatic tumors, especially in patients with liver metastases." (PMID 35982908, 2022).
ovarian carcinoma (1 paper, 2019). A malignant neoplasm originating from the surface ovarian epithelium. "We performed a systematic gene identification for these two histotypes of Japanese ovarian cancer and showed for the first time that CPNE8 plays oncogenic roles in ovarian CCC." (PMID 31487856, 2019). "Knockdown experiments showed that CPNE8 and BHLHE41—the former was CCC-predominant, and the latter was HGSC-predominant in PC1 by PCA—regulate the growth of ovarian cancer cells in a histotype-preferential manner." (PMID 31487856, 2019).
ovarian clear cell cancer (1 paper, 2024). An invasive malignant neoplasm that arises from the ovary and is characterized by a predominance of clear and hobnail malignant epithelial cells. "Ovarian clear cell carcinoma is dramatically inhibited by CPNE8 knockout studies." (PMID 39867879, 2024).
stomach adenocarcinoma (1 paper, 2022). "To identify candidate genes involved in GC progression and metastasis, we re-analyzed the TCGA stomach adenocarcinoma RNA-seq dataset and screened 16 genes that were highly expressed in GC and associated with metastasis, including CPNE8." (PMID 35982908, 2022).
tumor (7 papers, 2019 to 2024). "In addition, CPNE8 expression is associated with multiple immune cell infiltrations in the tumor microenvironment, which may lead to GC metastasis." (PMID 35982908, 2022). "In addition to their association with AML prognosis, CPNE8, HOXA10, and SPINT2 were also found to be prognostically relevant across multiple tumor types." (PMID 39555062, 2024). "Furthermore, high levels of CPNE8 can recruit more CAFs and involve immune pathways in the tumor microenvironment." (PMID 35982908, 2022). "CPNE8 might promote tumor proliferative capacity by accelerating the G1-S phase transition of the cell cycle." (PMID 35982908, 2022). "Our findings suggest that CPNE8 modulates focal adhesion and tumor microenvironment to promote GC progression and invasiveness and could serve as a novel prognostic biomarker in GC." (PMID 35982908, 2022). "The group with CPNE8 overexpression showed a significant increase in tumor weight." (PMID 35982908, 2022). "Moreover, our results showed that GC cells with high CPNE8 expression demonstrated enhanced invasion and migration abilities, thus providing a basis for tumor metastasis." (PMID 35982908, 2022). "CPNE8, a member of the Copine family, is related to a variety of tumor development." (PMID 34663825, 2021). "In addition, CPNE8, a critical core factor of tumor metastasis, triggers the focal adhesion pathway by upregulating FAK and ERK expression and activating CAFs in the tumor microenvironment by regulating chemokines and their receptors, leading to a suppressed immune response." (PMID 35982908, 2022). "Interestingly, upregulated DEGs like SNCG (logFC 9.95), CPNE8 (logFC 7.18), GRIA3 (logFC 4.08), SOX5 (logFC 3.94) and CRISP3 (logFC 3.44) representing the highest log fold changes were involved in tumor cell metastasis and invasiveness." (PMID 37239828, 2023). "In this study, 9 tumor-infiltrating immune cells were significantly correlated with the expression of CPNE8, among which B cells naive, mast cells resting, monocytes, T cells CD4 memory resting, and T cells regulatory (Tregs) were positively correlated with the expression of CPNE8." (PMID 34663825, 2021).
cancer (3 papers, 2021 to 2023). A tumor composed of atypical neoplastic, often pleomorphic cells that invade other tissues. "Accumulating evidence suggests that CPNE8 functions in cancer cell migration and invasion." (PMID 35982908, 2022). "The most significantly upregulated DEGs such as SNCG, CPNE8, GRIA3, SOX5 and CRISP3 can be involved in metastasis and invasivity of cancer cells as well." (PMID 37239828, 2023). "Interestingly, we assessed the mRNA levels of the chemokine receptors CCR4 and CXCR4 in GC cells and found that knockdown or overexpression of CPNE8 significantly regulated their expression, implying that CPNE8 may affect the function of CAFs via modulation of chemokine binding to cancer cells." (PMID 35982908, 2022). "First, the GSEA and KEGG results showed that the high CPNE8 expression group was functionally enriched in focal adhesion, gap junction, and ECM receptor interaction in the TCGA-STAD cohort, which were correlated with cancer metastasis 35-37." (PMID 35982908, 2022). "The expression level of CPNE8 was significantly related to grade (P = 0.043) and TNM stage (P = 0.027).Gene set enrichment analysis showed that they might participate in GC progression through cancer-related pathways." (PMID 34663825, 2021).
adenocarcinoma (1 paper, 2019). A common cancer characterized by the presence of malignant glandular cells. "Adenocarcinoma-derived SKOV3 cells partially expressed both the CCC-related marker CPNE8 and the HGSC-related marker NOL4L." (PMID 31487856, 2019).
immune dysfunction (1 paper, 2022). "CPNE8 expression was positively correlated with immune dysfunction and TIDE scores in our study." (PMID 35982908, 2022).
CPNE8 also shares sentences with these, for which no sentence is quoted: breast tumor (1 paper); Graves disease (1); Obesity (1).